BCYRN1 (brain cytoplasmic RNA 1)
Diseases named in the same sentence as BCYRN1 in open-access papers (continued):
Sharing a sentence is not in itself a finding about the gene and the disease.
bladder cancer (11 papers, 2021 to 2025). "Exosomal BCYRN1 has been reported to be associated with lymph node metastasis of bladder cancer, and, higher expression of BCYRN1 represented poorer prognosis." (PMID 37805491, 2023). "lncRNA BCYRN1 is upregulated in urinary exosomes from bladder cancer (BCa) patients and associated with LN metastasis and poor prognosis of patients." (PMID 34323412, 2021). "Long non-coding RNAs such as BCYRN1 (BCYRN1 non-coding RNA) are substantially upregulated in urine-derived exosomes of bladder cancer patients and correlate with lymph node metastasis and poor prognosis." (PMID 41459253, 2025). "Long non-coding RNA BCYRN1 in urine-derived exosomes of bladder cancer patients positively correlates with shorter survival and has been identified as an independent poor prognostic factor." (PMID 41459253, 2025). "Blood exosomes from 31 bladder cancer patients and 19 healthy controls were collected and quantification of BCYRN1 showed increased expression of BCYRN1 in patients with bladder cancer." (PMID 40075875, 2025). "Given that knocking down BCYRN1 reduces the activity of bladder cancer cells, we investigated the possibility of using serum BCYRN1 as a biomarker." (PMID 38892143, 2024). "Several lncRNAs, including LINC00839, lncRNA PVT1, LUCAT1, LINC00958, and BCYRN1, exert a positive influence on both the proliferative viability and invasive capabilities of bladder cancer cells." (PMID 39628486, 2024). "They found that BCYRN1 is transported via exosomes from bladder cancer cells to LECs, where it stabilizes VEGFR-3 mRNA by interacting with its 3′‐UTR." (PMID 37407839, 2023). "In addition, a decrease in BCYRN1 expression was observed in eight patients who underwent complete resection of bladder cancer." (PMID 40075875, 2025). "The authors proposed a dual mechanism of action for BCYRN1 in bladder cancer." (PMID 37407839, 2023). "So, BCYRN1 can be a therapeutic target for patients with bladder cancer." (PMID 36463254, 2022). "Knockdown of lncRNA brain cytoplasmic RNA 1 (BCYRN1) in T24 and BOY bladder cancer cells suppressed proliferation, migration, and invasion." (PMID 40075875, 2025). "Also, BCYRN1 increases VEGFC and its receptor (VEGF‐C/VEGFR3) signaling in bladder cancer patients with lymph node metastatic." (PMID 36463254, 2022). "Thus, BCYRN1 simultaneously increases both VEGFR-3 expression in LECs and VEGF-C secretion from bladder cancer cells, creating a feedforward loop that promotes tumor lymphangiogenesis and LN metastasis in bladder cancer through amplified VEGF‐C/VEGFR-3 signaling." (PMID 37407839, 2023).
colorectal cancer (10 papers, 2019 to 2025). A primary or metastatic malignant neoplasm that affects the colon or rectum. "Likewise, BCYRN1 overexpression was linked to larger tumors and advanced pathological stages in colorectal cancer patients." (PMID 35874631, 2022). "It has been proved that the lncRNA BCYRN1 affected the occurrence and development of colorectal cancer by regulating the effects of miR-204-3p on KRAS." (PMID 40764575, 2025). "Overexpression of BCYRN1 competitively bound with miR‐204‐3p to regulate the tumorigenesis of colorectal cancer." (PMID 34323412, 2021). "In addition, Yu and Chen reported that the aberrantly high expression of BCYRN1 in colorectal cancer tissues increased metastasis and worsened patient prognosis." (PMID 35874631, 2022). "The upregulation of BCYRN1 in colorectal cancer was reported in four studies." (PMID 35874631, 2022). "However, the roles of BCYRN1 in colorectal cancer (CRC) remain obscure." (PMID 32944001, 2020).
asthma (8 papers, 2017 to 2025). "A similar study, using rat model asthma, demonstrated that miR-150 downregulates BCYRN1 and reduces proliferation and migration of ASMCs (Zhang X.-y." (PMID 34819948, 2021). "The lncRNA BCYRN1 similarly increased airway smooth muscle proliferation and migration in an asthma model." (PMID 30941157, 2019). "The miR-150/ lncRNA BCYRN1 axis was targeted by Sch B treatment, leading to suppression of cell proliferation in asthma." (PMID 31178721, 2019). "Using a rat model of asthma, the authors demonstrated increased expression of BCYRN1 in sensitized rats as compared to control animals." (PMID 29186897, 2017). "For example, BCYRN1 could upregulate the expression of transient receptor potential and thus promoted migration of rat airway smooth muscle cells in asthma." (PMID 29435146, 2018). "For example, in the rat model of asthma, upregulation of brain cytoplasmic RNA 1 (BCYRN1) lncRNA targets canonical transient receptor potential 1 (TRPC1), which is implicated in the pro-proliferative and pro-migratory role of BCYRN1 and induces proliferation and migration of ASMCs (Zhang XY." (PMID 34819948, 2021). "Moreover, Sch B can mediate ceRNA crosstalk between miR-150 and lncRNA BCYRN1, further establishing an miR-150/lncRNA BCYRN1/cell proliferation axis; however, as a new regulatory mechanism influencing asthma, the stability of the ceRNA crosstalk requires further investigation." (PMID 31178721, 2019). "Another study analyzing long ncRNAs found that brain cytoplasmic RNA 1 (BCYRN1) was dysregulated in airway smooth muscle (ASM) cells, which are crucial during bronchial remodeling in asthma." (PMID 29186897, 2017).
gastric cancer (8 papers, 2018 to 2024). A primary or metastatic malignant neoplasm involving the stomach. "Zhai and Li found that BCYRN1 is highly expressed in gastric cancer tissues and controls gastric cancer cell proliferation, cell cycle, migration, and invasion by targeting miR-204-5p." (PMID 35874631, 2022). "In the present study, we showed that the increased expression of BCYRN1 promoted cell proliferation and migration, and suppressed apoptosis in gastric carcinoma." (PMID 29435146, 2018). "There are two reports investigating the link between BCYRN1 expression and stomach cancer." (PMID 35874631, 2022). "However, the expression of BCYRN1 and its roles in gastric carcinoma (GC) still remain unidentified." (PMID 29435146, 2018). "Long non-coding RNA brain cytoplasmic RNA 1 (BCYRN1) has been found to play an important role in tumorigenesis of a variety of tumors including gastric cancer (GC)." (PMID 31652309, 2019). "Either as an oncogenic lncRNA or a tumor suppressor, BCYRN1 was reported to exert significant biological function in cancers such as NSCLC, ovarian cancer, and gastric cancer." (PMID 32978519, 2020).
hepatocellular carcinoma (8 papers, 2020 to 2025). A malignant tumor that arises from hepatocytes. "It is reported that miR-490-3p overexpression significantly inhibited the proliferation, invasion, and migration of hepatocellular carcinoma cells by activating BCYRN1." (PMID 34987577, 2021). "BCYRN1 was found to regulate some cancer-related pathways through the lncRNA-miRNA-mRNA network and promote the occurrence of hepatocellular carcinoma (HCC), thus providing a new perspective for exploring the pathogenesis of HCC as a potential diagnostic and prognostic biomarker." (PMID 37465460, 2023). "In the hepatocellular carcinoma (HCC), BCYRN1 might regulate some cancer‐related pathways to promote HCC initiation via an lncRNA‐miRNA‐mRNA network." (PMID 32233022, 2020). "However, research about function of BCYRN1 in hepatocellular carcinoma (HCC) is limited." (PMID 31920461, 2020).
cervical carcinoma (5 papers, 2018 to 2022). A carcinoma arising from either the exocervical squamous epithelium or the endocervical glandular epithelium. "BCYRN1 knockdown in cervical cancer has also been shown to disrupt tumor growth, reduce MMP3 and VEGF expression, and enhance miR-138 expression." (PMID 35730016, 2022). "In HeLa cervical carcinoma cells, depletion of BCYRN1 disrupted the cellular motility by destabilizing mRNA for calcium-binding protein S100A11." (PMID 29435146, 2018).
esophageal squamous cell carcinoma (5 papers, 2018 to 2022). Esophageal squamous cell carcinoma (ESCC) is a type of esophageal carcinoma (EC) that can affect any part of the esophagus, but is usually located in the upper or middle third. "The predicted top five lncRNAs are MALAT1, MEG3, BCYRN1, UCA1, and LSINCT5, among which MALAT1 and MEG3 are found to be associated with esophageal squamous-cell carcinoma in lncRNADisease in 2017." (PMID 35186029, 2022). "Although we have not manually excavated recent literature to prove that BCYRN1 is related to esophageal squamous-cell carcinoma, we believe that scientists will find the evidence that BCYRN1 is associated with esophageal squamous-cell carcinoma in the future." (PMID 35186029, 2022).
lymph node metastasis (4 papers, 2019 to 2025). "To further explore the clinical value of BCYRN1 in GC patients, we estimated the association between BCYRN1 expression and clinicopathological characteristics, and found that BCYRN1 expression was closely correlated with tumor depth, lymph node metastasis and clinical stage in patients with GC." (PMID 31652309, 2019).
prostate carcinoma (4 papers, 2016 to 2024). A carcinoma that arises from epithelial cells of the prostate gland. "BCYRN1 was reported to promote prostate cancer progression, and it is described as solely an oncogene, which is also the case of LINC00152, SNHG5 and LINC00313." (PMID 35205253, 2022). "Two studies so far have analyzed the relationship between BCYRN1 expression and prostate cancer." (PMID 35874631, 2022).
bladder tumor (2 papers, 2022 to 2024). "We also observed that serum exosomal BCYRN1 expression was markedly reduced after the complete dissection of bladder tumors, and patients who exhibited reduced BCYRN1 expression showed no recurrence after surgery for more than 2 years." (PMID 38892143, 2024). "Serum exosomal BCYRN1 levels significantly decreased with complete resection of BC but did not decrease in a patient with a residual bladder tumor after resection." (PMID 38892143, 2024). "In contrast, one patient whose serum exosomal BCYRN1 was not reduced after the first TUR showed the presence of a bladder tumor on the second TUR surgery and local recurrence within one year." (PMID 38892143, 2024).
liver cancer (2 papers, 2021 to 2022). An epithelial or non-epithelial malignant neoplasm that arises from the liver. "Three studies analyzed the relationship between BCYRN1 and liver cancer and reported upregulation of BCYRN1 in the tumor tissues." (PMID 35874631, 2022).
NK/T-cell lymphoma (2 papers, 2023 to 2024).
parathyroid carcinomas (2 papers, 2022 to 2024). "Particularly, we found that the lncRNA BC200/BCYRN1 could represent a candidate biomarker for parathyroid carcinomas (PCas)." (PMID 35586620, 2022).
Autoimmunity (1 paper, 2025). The occurrence of an immune reaction against the organism's own cells or tissues. "While we studied BCYRN1 overexpression in the context of ischemic injury here, the same approach merits testing in other disease processes (e.g., autoimmunity or transplant rejection) where increased Treg activity is a recognized therapeutic goal." (PMID 40131367, 2025).
hepatitis B (1 paper, 2020). "Plasma BCYRN1 expression of HCC patients was significantly higher than that of healthy controls (p < 0.001) or hepatitis B patients (p < 0.01)." (PMID 33061848, 2020). "The authors analyzed BCYRN1 expression in plasma from 124 HCC patients, 79 cirrhosis patients, 68 hepatitis B patients and 74 healthy controls." (PMID 33061848, 2020).
lentivirus infection (1 paper, 2015). Virus diseases caused by the Lentivirus genus. "RNA interference and lentivirus infection showed a positive correlation between the expressions of c-MYC and BCYRN1." (PMID 25866480, 2015).
myocardial infarction (1 paper, 2025). Gross necrosis of the myocardium, as a result of interruption of the blood supply to the area, as in coronary thrombosis. "In a mouse model of myocardial infarction, CDC-EVs, particularly those overexpressing BCYRN1, were cardioprotective, reducing infarct size and troponin I levels even when administered after reperfusion." (PMID 40131367, 2025).
osteosarcoma (1 paper, 2025). A usually aggressive malignant bone-forming mesenchymal neoplasm, predominantly affecting adolescents and young adults. "The expression of BCYRN1 in osteosarcoma cells was significantly decreased after the treatment of HCSI." (PMID 40764575, 2025). "The BCYRN1-miR-27a-3p-HMGCR axis was subsequently screened as the primary ceRNA regulatory network in HSCI against osteosarcoma." (PMID 40764575, 2025). "HCSI could inhibit osteosarcoma progression by regulating lipid metabolism through BCYRN1-miR-27a-3p-HMGCR axis, indicating that HCSI may provide insights for developing herbal medicine injection-based therapies for osteosarcoma." (PMID 40764575, 2025). "Therefore, the combination enhanced the level of apoptosis in osteosarcoma cells and down-regulating the expression of Bcl-2/Bax by HMGCR-miR-27a-3p-BCYRN1 axis." (PMID 40764575, 2025).
pc (1 paper, 2022). "Expression of the lncRNA BCYRN1 was increased 6.2-fold, and it was ranked 82 of all of the detected lncRNAs in the EBV tumors and ranked 465 in the pc tumors." (PMID 35435703, 2022).
tumor (36 papers, 2015 to 2025). "Recently, several lncRNAs, including brain Cytoplasmic RNA 1 (BCYRN1), have been reported to be associated with tumor progression, metastasis, and acquired anticancer drug resistance." (PMID 38892143, 2024). "To explore the in vivo relevance of BCYRN1 in a xenograft model of HCC, we next stably transfected HCC cells with lentiviruses encoding sh-NC or sh-BCYRN1 and monitored tumor formation following subcutaneous implantation in nude mice." (PMID 35730016, 2022). "Meta-analysis revealed that increased BCYRN1 expression was associated with both overall tumor survival (OS; HR = 1.84, 95% CI 1.51–2.25, p < 0.0001) and disease-free survival (DFS; HR = 1.65, 95% CI 1.20–2.26, p=0.002)." (PMID 35874631, 2022). "Another study reported an association between BCYRN1 and advanced tumor stage and metastasis in NSCLC patients." (PMID 35874631, 2022). "In the present study, we found BCYRN1 expression was dramatically elevated in GC tissues and cell lines, and positively associated with tumor depth, lymph node metastasis and clinical stage in patients with GC." (PMID 31652309, 2019). "Additionally, gene set enrichment analysis (GSEA) using RNA sequences from tumor fractions showed that BCYRN1 downregulation decreased the expression of mRNAs associated with the cell cycle." (PMID 38892143, 2024). "Furthermore, a strong association was discovered between increased BCYRN1 expression and tumor invasion depth (OR = 2.11, 95% CI 1.49–2.99, p=0.000), clinical stage (OR = 2.52, 95% CI 1.18–5.37, p=0.017), and distant tumor metastasis (OR = 4.19, 95% CI 1.45–12.05, p=0.008)." (PMID 35874631, 2022). "The downregulation of BCYRN1 significantly decreased tumor volume, with significant differences in tumor volume and tumor weight observed over time." (PMID 38892143, 2024). "For example, in CRC, the lncRNA BCYRN1 promotes tumour cell proliferation by upregulating NPR3, which confirms that NPR3 is a promoter in CRC29." (PMID 37076508, 2023). "The high expression of BCYRN1 in various tumor cell lines suggests the role of BCYRN1 as an oncogenic lncRNA." (PMID 34489556, 2022). "From a mechanistic perspective, BATF was recruited to the TM4SF1 promoter by BCYRN1, and reducing the expression of this lncRNA was sufficient to constrain xenograft tumor growth in mice." (PMID 35730016, 2022). "Elevated BCYRN1 expression is correlated to worse prognosis and clinicopathological features (including T stage, clinical stage, and distant tumor metastasis) in cancer patients." (PMID 35874631, 2022). "Herein, we found that BCYRN1 was upregulated in HCC patient tumor tissues and that the degree of such upregulation was associated with decreased patient OS." (PMID 35730016, 2022). "Overall, our data show that BCYRN1 can enhance TM4SF1 expression in a BATF recruitment-dependent fashion to modulate tumor malignancy, thereby enhancing HCC cell migration, invasion, and proliferation." (PMID 35730016, 2022). "From a functional perspective, BCYRN1 has previously been shown to influence tumor cell growth, apoptosis, and signal transduction through diverse complex pathways." (PMID 35730016, 2022). "Mechanically, BCYRN1 sponges endogenous tumor suppressor miR-125a-5p to de-depress the expression of TAZ (transcriptional coactivator with PDZ-binding motif)." (PMID 33995499, 2021). "The observation that BCYRN1 significantly promoted the lymphangiogenesis and LN metastasis of BCa prompted us to explore the regulatory role of BCYRN1 in the secretion of VEGF‐C which is the crucial inducer of tumor lymphangiogenesis." (PMID 34323412, 2021). "In BCYRN1-overexpressed xenograft models, tumor growth rate was significantly higher than BCYRN1-knockdown models." (PMID 33391513, 2021). "Since tumorigenicity is vital for tumor LN metastasis, we first evaluated the oncogenic function of BCYRN1 in the tumorigenicity of BCa by constructing the subcutaneous xenograft model." (PMID 34323412, 2021).